ZNF584 (zinc finger protein 584)
Description:
May be involved in transcriptional regulation.
Synonyms: FLJ39899
Tractability: No criterion of Open Targets' tractability assessment is met for any kind of drug.
Gene: Protein-coding gene on chromosome 19 (58,401,504 to 58,431,736, forward strand). Ensembl gene ENSG00000171574.
Subcellular location: Nucleus
Subcellular location (Human Protein Atlas): Nuclear speckles
Pathways (Reactome):
Gene expression (Transcription): Generic Transcription Pathway
Gene Ontology:
Molecular function: DNA-binding transcription factor activity, RNA polymerase II-specific; RNA polymerase II cis-regulatory region sequence-specific DNA binding
Biological process: regulation of transcription by RNA polymerase II; regulation of DNA-templated transcription
Cellular component: nucleus
Genetic constraint (gnomAD): Loss-of-function variants: 12 observed, 13.52 expected, observed/expected ratio (o/e) 0.89, 90% interval 0.57 to 1.43. The upper end of that interval is the gene's LOEUF score, 1.43, which puts it in group 5 of 6, group 1 being the genes least tolerant of losing a copy. Missense variants: 451 observed, 512.63 expected, observed/expected ratio (o/e) 0.88, 90% interval 0.81 to 0.95. Synonymous variants: 198 observed, 191.08 expected, observed/expected ratio (o/e) 1.04, 90% interval 0.92 to 1.17.
Homologues: Orthologues: chimpanzee ZNF584 (99% identical), macaque ZNF584 (94% identical), dog ZNF584 (77% identical), pig ZNF584 (73% identical), rabbit ZNF584 (62% identical), guinea pig ZNF584 (59% identical), rat Zfy1 (20% identical), zebrafish zfx (20% identical), mouse Zfy1 (19% identical), mouse Zfy2 (19% identical), tropical clawed frog zfx (18% identical). Paralogues in human: ZNF792 (45% identical), ZNF548 (45% identical), ZNF256 (44% identical), ZNF551 (44% identical), ZNF304 (43% identical), ZNF549 (42% identical), ZNF587B (41% identical), ZNF418 (40% identical), ZNF773 (40% identical), ZNF419 (40% identical), ZNF586 (39% identical), ZNF480 (39% identical), and 26 more.